ALDH1A1 (aldehyde dehydrogenase 1 family member A1)
Diseases named in the same sentence as ALDH1A1 in open-access papers (continued):
Sharing a sentence is not in itself a finding about the gene and the disease.
tumor (continued). "Identified as a marker for numerous tumor-initiating cells, ALDH1A1 contributes to maintaining the stemness of tumor cells, promoting tumor angiogenesis and metastasis, and playing a pivotal role in the development of resistance to anticancer drugs." (PMID 39107297, 2024). "Through ALDH1A1 knockdown and compensation experiments, it was established that ALDH1A1 serves as an upstream driver of glycolytic effects in tumor cells." (PMID 39107297, 2024). "The pre-coculture with CAFs increased the tumor-initiating cell frequency 10-fold, with an increase in ALDH1A1 expression in the pre-cocultured tumors, further confirming the role of CAFs in inducing OCSCs." (PMID 38191909, 2024). "The aldehyde dehydrogenase 1A1 (ALDH1A1) isoform, which can positively regulate tumor cell survival in circulation, extravasation, and metastatic dissemination, is correlated with Aldefluor activity in PCa patients’ tissue specimens." (PMID 39335669, 2024). "Our analysis revealed an overexpression of the ALDH1A1 gene in the tumor bone metastatic cells compared to cells derived from primary tumors." (PMID 38169509, 2024). "Specifically, ALDH1A1 upregulates ZBTB7B in tumor cells, subsequently promoting the upregulation of LDHA." (PMID 39107297, 2024). "ALDH1A1 is suggested to participate in the maintenance of CSCs and is known as a marker for lung CSCs, which have high tumor-initiating and self-renewing capabilities." (PMID 39272828, 2024). "This includes factors related to tumor and patient selection, as well as the cut‐off for ALDH1A1 overexpression." (PMID 38400679, 2024). "The combination of ALDH1A1 inhibitors and PD-1 mAb represents a promising therapeutic strategy to mitigate tumor immune escape." (PMID 39107297, 2024). "Other evidence, based on studies with heterogeneous receptor status, suggests ALDH1A1 as a biomarker predicting tumor progression and poor survival in BC patients." (PMID 38400679, 2024). "GSEA confirmed that genes downregulated in response to the ALDH1A1 knockdown were enriched in the datasets associated with WNT/β-catenin signaling, epithelial-mesenchymal transition, and tumor invasion." (PMID 38169509, 2024). "The co-administration of PD-1 mAb and an ALDH1A1 antagonist enhances the anti-tumor therapeutic effect by augmenting the activity of killer CD8+ T cells." (PMID 39107297, 2024). "The convergence of ALDH1A1 inhibition and immune checkpoint blockade, particularly with PD-L1/PD-1 mAb, presents a compelling avenue for curtailing tumor immune escape." (PMID 39107297, 2024). "In 2022, Wang and colleagues discovered that targeting ALDH1A1 can inhibit tumor viability through the WNT pathway in the invasion of MKN-45 cells." (PMID 39796106, 2024). "In neoplasia, ALDH1A1 and ALDH1A3 isoforms have been implicated as tumor-promoting factors and universal biomarkers of cancer stem cells (CSCs), including GSCs." (PMID 39513909, 2024). "For the first time, we showed that the level of ALDH1A1 is upregulated in distant metastases compared to the primary tumor sites, and the expression of ALDH1A3 has an opposite regulation." (PMID 38169509, 2024). "This experiment showed that cells depleted for Aldh1a1 formed a lower number of tumor nodules when compared to the control." (PMID 38169509, 2024). "Further analysis demonstrated elevated ALDH1A1 expression in pathologically diagnosed high-grade (poorly differentiated) tumor tissues." (PMID 39107297, 2024). "In confirmation, immunoblotting revealed a dose dependent reduction in expression of CSC makers (Sox2, Oct4, Nanog and ALDH1A1) in the ART-treated tumors compared to the untreated tumor." (PMID 38144525, 2023). "However, the clinical relevance of ALDH1A1 in CRCs remains controversial, although an association between the increased expression of ALDH1A1 and clinicopathological parameters, such as larger tumor size, higher histological grade, greater possibility of LNM has been observed across several studies." (PMID 36694633, 2023).
tumor (continued). "We found that FAT1 was significantly increased in Z8-treated xenografts in addition to the retention of YAP1 in the cytoplasm of tumor cells and suppression of ALDH1A1." (PMID 37147285, 2023). "We observed varying degrees of decrease in the fluorescence intensity of Oct4, Sox2, Aldh1a1, Epcam, and Itgb1 in tumor tissues formed by 66cl4-shSix1 KD1-luc and 66cl4-shSix1 KD2-luc compared to those formed by 66cl4-SCR-luc." (PMID 38031089, 2023). "Both normal stem cells and stem-like cells that initiate tumours have their biological functions controlled by ALDH1A1, which encourages tumour growth and chemotherapy resistance." (PMID 36768291, 2023). "In order to test if tEVsCSC preferentially interact with specific immune cell subsets, we challenged mice with mEER tumor cells carrying the ALDH1A1:CD63-eGFP or the SRE:CD63-eGFP expression cassette." (PMID 36735677, 2023). "Tumour cells with strong positive ALDH1A1 expression accounted for approximately 38.8% of the total cells and were localised in crypts, showing a spatial distribution similar to that of normal stem cells." (PMID 36651035, 2023). "This study used the patient-derived organoid models to show the inhibitory role of ALDH1A1 in bringing back the tumor sensitivity." (PMID 37645246, 2023). "Downregulation of PrPC caused by melatonin can prevent the expression of the stem cell markers Oct4, Nanog, Sox2 and ALDH1A1, which inhibits tumour development, proliferation and tumour-mediated angiogenesis by affecting ISCs." (PMID 37101229, 2023). "ADSC also influence the sphere formation and tumor initiation of BC, along with increased expression of stem markers ALDH1A1 and ABCG2." (PMID 37445860, 2023). "Silybin reduced tumor growth when ALDH1A1+ prostate cancer DU145 cells were transplanted into nude mice." (PMID 37569466, 2023). "CSCs with high ALDH1A1 activity in these tumors are endowed with highly tumorigenic potential, enhanced capability of self‐renewal, and recapitulation of parental tumor heterogeneity." (PMID 36694633, 2023). "The expression of ALDH1A1 was reduced in human and mouse tumor tissues compared to a normal pancreas." (PMID 37569466, 2023). "It has been shown that the Notch signaling pathway plays a special role in inducing carcinogenesis and tumor growth by re-activating post-translationally inactivated ALDH1A1." (PMID 37686694, 2023). "The tumor histopathology was confirmed by H&E staining; ALDH1A1 expression in these tissues was assessed using IHC." (PMID 37429899, 2023). "Considering the TI values calculated for the compounds, as well as the ALDH1A1 values, the most promising compound is with anti-tumor properties against the DU145 line is WZ2." (PMID 38139832, 2023). "In positive samples, ALDH1A1+ cells accounted for more than 50% of the total tumour cells in 47% of the samples." (PMID 36651035, 2023). "Cell viability analyses showed that NCT-505 and olaparib can synergistically reduce tumor cell viability in OV35 and OV39 HGSOC tumor organoids, which possess BRCA2 and BRCA1 mutation, respectively, as well as positive ALDH1A1 expression." (PMID 37429899, 2023). "Combination treatment with olaparib and the ALDH1A1 inhibitor is able to synergistically reduce tumor cell viability in the PDOs with mutated BRCA1/2 and positive ALDH1A1 expression." (PMID 37429899, 2023). "The authors’ ongoing study shows that an ALDH 1A1+1A3 peptide-DC vaccine elicits significantly stronger T cell and B cell immune responses against the tumor, compared with an ALDH1A1 or ALDH1A3 peptide-DC vaccine alone." (PMID 37251931, 2023). "Microarray analysis of ALDEFLUOR+ and ALDEFLUOR– cells isolated from xenografted tumours indicated that the expression of ALDH1A1 and ALDH1A3 was more than 15 times higher in the ALDEFLUOR+ subpopulation." (PMID 36651035, 2023). "To this end, we performed immunofluorescence staining for CD45 and F4/80 on tumor sections from mice carrying either PGK:CD63-eGFP or ALDH1A1:CD63-eGFP expressing tumors." (PMID 36735677, 2023).
tumor (continued). "IL-6-Nab combined with HMA completely eradicated OCSCs, and this combination blocked IL-6/IL6-R/pSTAT3-mediated ALDH1A1 expression, providing a strategy for tumor recurrence after chemotherapy." (PMID 36387165, 2022). "This suggested that the expression levels of ALDH1A1 at different degrees of tumor development changed dynamically." (PMID 36484016, 2022). "ALDH1A1/B1 showed weak correlation with the six key types of immune cell in the tumor microenvironment." (PMID 35280765, 2022). "Aldehyde dehydrogenase 1A1 (ALDH1A1) is associated with the capacities of self-renewal, differentiation, and tumor initiation." (PMID 35008958, 2022). "We found that the expression level of ALDH1A1 was negatively correlated with tumor cell necroptosis and positively correlated with oxidative phosphorylation." (PMID 36484016, 2022). "IHC analysis showed that overexpression of RICH1 significantly inhibited the expression of YAP/TAZ and CSCs-associated markers (ALDH1A1, NANOG, OCT4, and SOX2) in transplanted tumor tissues." (PMID 35064101, 2022). "On the other hand, tumor-sphere in A549 cells expressed only three genes (ALDH1A1, Oct4, and Sox2), and dinactin significantly reduced the relative expression of only ALDH1A1." (PMID 36551502, 2022). "In line with ALDH1A1 depletion, A37 largely impaired tumour growth and prolonged survival of mice bearing CrT/TICs." (PMID 36504325, 2022). "In their study, the group with high ALDH1A1 levels was significantly associated with low serum levels of AFP, a small tumor diameter, low levels of lymphovascular invasion, a more differentiated pathology, and a less advanced stage." (PMID 35814382, 2022). "Overall, moderate to strong expression of SOX2 and ALDH1A1 was observed more frequently in tumor buds than in the main tumor body (51.7% vs. 9.2%; 48.3% vs. 20.7%, respectively; both P < 0.001)." (PMID 35860042, 2022). "Medroxyprogesterone acetate (MPA) can increase the expression of CD44 and the activity of ALDH1A1 in BCSCs, enhance the tumorigenesis of CSCs and block cholesterol synthesis, which can reduce the formation of tumor spheres in BCSCs." (PMID 36497050, 2022). "DkkMo reduced the expression of Dkk-1 and Aldh1a1, reduced expansion of OS tumours, preserved bone volume and architecture and stimulated tumour necrosis." (PMID 35277659, 2022). "NANOG also works together with other stemness factors, such as MYC, OCT4, KLF4, SOX2, SOCS2, or ALDH1A1, to control a set of target genes that have important functions in embryonic stem cells and, plausibly, in tumor cells." (PMID 35104240, 2022). "The ALDH1A1 expression on tumor treatment with INJ, PUMP (ASA), PUMP (OP) and PUMP (ASA + OP) in combination with GEM was significantly reduced compared to GEM treatment." (PMID 35892853, 2022). "Our choice of SC markers was based on our report in the BM18 xenograft model of PC that cells surviving castration and able to reinitiate tumor growth are characterized by the coexpression of ALDH1A1 or NANOG together with the luminal marker NKX3-1." (PMID 36185585, 2022). "Consistent with our expectations, we observed high expression of SOX2 and ALDH1A1 in CxSCC tumor buds." (PMID 35860042, 2022). "In this study, we found that ALDH1A1 was down-regulated in most tumor cells compared to normal cells, but its role in different tumors was diverse." (PMID 36484016, 2022). "Here, we show that the knockdown of TUBB4B downregulates the expression of pluripotency markers, depletes ALDH1A1+ population, decreases in vitro sphere formation, and diminishes the tumor initiation potential in vivo." (PMID 35004310, 2021). "Subsequently, to investigate the effect of these drugs in the tumor xenografts, we performed IHC staining for cell proliferative marker Ki-67, ALDH1A1, and RNA-ISH for DLX1 expression." (PMID 34493733, 2021).
tumor (continued). "Knockdown of ALDH1A1 markedly inhibited cell proliferation and increased sensitivity to GEM, indicating a vital functional role of ALDH1A1 in maintaining drug resistance in tumor cells." (PMID 34453639, 2021). "Double immunostaining with the tumor stem cell marker ALDH1A1 maintaining CSC properties indeed showed colocalization of VEGFR2 with ALDH1A1." (PMID 34680369, 2021). "In contrast, the cell surface stem cell indicator ALDH1A1 remained intact in the dissected H1975 spheroid tumor tissues within the concentration ranges." (PMID 35582384, 2021). "A member of the aldehyde dehydrogenase protein family, ALDH1A1 expressed in a subpopulation of tumour-initiating cells and is therefore a potential candidate biomarker for cancer therapy." (PMID 33800113, 2021). "Expression of ZEB1, BMI1, and ALDH1A1 was analyzed by immunohistochemistry in tumor specimens from NSCLC patients with acquired resistance to gefitinib." (PMID 33764690, 2021). "Taken together, these findings indicated that ZEB1, BMI1, and ALDH1A1 were highly expressed in tumor specimens from NSCLC patients with acquired resistance to gefitinib." (PMID 33764690, 2021). "We then revealed that CSC score (based on CD44, CD24, and ALDH1A1) was correlated with tumor progression and TB." (PMID 35083162, 2021). "Contradictory to this data we previously characterized CSCs of OPC and had been successful to isolate CSCs by ALDH1A1 marker and CSCs have the ability to form tumor spheres." (PMID 34359786, 2021). "ALDH1 (specifically isoform ALDH1A1) is another recently identified CSC marker in different tumours and regulates the oxidation of retinal substrates into retinoic acid." (PMID 34638469, 2021). "Apart from the RAR signaling, ALDH1A1 promotes a self-renewing population through tumor growth, self-protection by anti-oxidant activity and the development of drug resistance by its catalytic potential." (PMID 34150761, 2021). "Our group isolated CSCs from HPV-negative cell line of UT-SCC 60A by CSC marker ALDH1A1 and showed that CSCs formed tumor spheres." (PMID 34359786, 2021). "We found that high expression of ALDH1A1 protein and transcript level in the primary HCC tumor was associated with lower rates of recurrence post-LT." (PMID 34794390, 2021). "Further, aspirin also suppressed the enrichment of ALDH1A1+ TRCs and reduced the proportion of Ki-67+ cells in tumor tissues after radiotherapy." (PMID 32228703, 2020). "Quantitative RT-PCR analysis showed that the mRNA level of Aldh1a1 was decreased in shCSN6-expressing xenograft tumour samples." (PMID 32225170, 2020). "AXL receptor tyrosine kinase is highly expressed in H1299-sdCSCs and AXL knockdown with siAXLs significantly reduced tumour sphere formation and ALDH1A1 and SNAI2 (Slug) expression." (PMID 32051483, 2020). "When stratified by ethnicity and Gleason score, the ALDH1A1 transcription level in African‐American cases was significantly lower than that in normal tissues (p = 4.14 × 10−5), so was the tumor tissues in Gleason 6 and 7 (p = 4.09 × 10−5 and p = 1.40 × 10−2)." (PMID 33068330, 2020). "When the analysis was restricted to the luminal ER+ tumours, high BMI1 expression was associated with low expression of ALDH1A1 (P = 0.025), ALDH1A3 (P = 0.026), CD133 (P = 0.038), CD44 (P = 0.0001), CD24 (P = 0.004) and SOX10 (0.0006)." (PMID 32524353, 2020). "The elevated CD44v6 level was also correlated with higher tumor staging, whereas a decreasing level of ALDH1A1 was correlated with lower tumor staging." (PMID 32039729, 2020). "Immunohistochemistry (IHC) staining further showed that ALDH1A1+ cells were highly enriched after irradiation in PDX tumor tissues." (PMID 32228703, 2020). "Here, we analyze the involvement of ALDH1A1 in the acquisition of stemness phenotype in tumor cells, the regulation of tumor angiogenesis and metastases, and the acquisition of anticancer drug resistance and immune evasion." (PMID 35582039, 2020).
tumor (continued). "Tumor cells are characterized by an aberrant redox state and an increase of ALDH1A1 expression can be helpful as ROS scavenger." (PMID 35582039, 2020). "As for SCD1, it is necessary for the tumor sphere formation and expression of stem cell markers including ALDH1A1, Oct4 and Nanog." (PMID 32726752, 2020). "Our data suggest that ALDH1A1 supports amoeboid tumour-initiating features via regulation of ROS metabolism." (PMID 33082334, 2020). "The role of ALDH1A1 as robust marker of stemness has been reported in depth by several authors, but in the last decade the emerging role in tumor progression of this enzyme has been proposed." (PMID 35582039, 2020). "We found that ALDH1A1 expression level decreased along with tumor staging and was significantly decreased in stages III and IV compared with stage I tumor (p = 0.019 and p = 0.013)." (PMID 32039729, 2020). "In human HNSCCs, ALDH1A1 expression correlates with lower tumor differentiation and worse prognosis." (PMID 31181618, 2019). "All eight patient samples showed a broadly similar intensity of ALDH1A1 staining in the cancerous fraction (i.e., all had scores of 0 with <5% positive tumor cells), which is consistent with the FACS data." (PMID 31921651, 2019). "Effective knockdown of PVT1 in EAC cells using PVT1 ASOs resulted in decreased cell proliferation, invasion, colony formation, tumor sphere formation, and reduced proportion of ALDH1A1+ cells." (PMID 31601234, 2019). "When the same dataset was normalized by passage, tumor S24 was found to have the highest ALDH1A1 expression compared to all other tumors." (PMID 31181618, 2019). "Because ALDH1A1 is an intracellular protein, qRT-PCR was used to compare expression levels between the original tumor tissue and within the first three passages of cell cultures derived from patient samples S12, S15, S18, S22, and S24." (PMID 31181618, 2019). "Spheroid cells were highly positive for ALDH1A1 and hence displayed a phenotype reminiscent of tumor stem cells." (PMID 31181618, 2019). "The results showed that the expression level of ALDH1A1 was correlated with gender, tumor size, and tumor stage (P=0.001, 0.02, and 0.01, respectively)." (PMID 31341476, 2019). "In general, ALDH1A1 is a known maker of stem cells in normal tissues and various tumor types and regulates cellular processes like self-renewal, proliferation, and repression of apoptosis." (PMID 31181618, 2019). "Remarkably, human TNBC samples contained tumor elements co-expressing PD-L1 with ALDH1A1 and/or CD44v6." (PMID 30705400, 2019). "When the expression values were normalized by each patient individually, we observed much higher ALDH1A1 expression for samples S12, S22, and S24 in the original tumor than in cell culture." (PMID 31181618, 2019). "We implanted s.c. in nude mice MCF-7 ALDH1A1KD, MCF-7 ALDH1A1+ and Scr and monitored tumor growth up to 23 days after inoculation." (PMID 30541574, 2018). "The tumor vascularity, expressed as % of total, was highest in ALDH1A1+ and Scr specimen (2.032 vs 1.862%, respectively), while it was drastically reduced in ALDH1A1KD (0.599%)." (PMID 30541574, 2018). "According the CSCs model, the ALDH1A1 positive cells are responsible for drug resistance development and tumor progression." (PMID 30583585, 2018). "After validation of the ALDH1A1 antibody, we next correlated ALDH1A1 expression to tumor differentiation." (PMID 30308036, 2018). "Our data and previous work thus warrants further research into targeting ALDH1A1 to prevent therapy resistance and tumor recurrence after treatment." (PMID 30308036, 2018). "Evaluation of VEGF expression as mRNA and protein in tumor explants, revealed its highest levels in ALDH1A1+ and Scr tumor specimen, whereas it was strongly downregulated in ALDH1A1KD tumors." (PMID 30541574, 2018). "ALDH1A1 mRNA and protein levels were then related to overall survival and to clinical, histopathological and molecular tumor features." (PMID 30308036, 2018).